IGF1 (insulin like growth factor 1)
Diseases named in the same sentence as IGF1 in open-access papers (continued):
Sharing a sentence is not in itself a finding about the gene and the disease.
acromegaly (continued). "Consistent with findings from previous series of acromegaly with pure GH-PAs, our study revealed that patients with GH&PRL-PAs who had a Knosp grade >2 along with higher serum GH and IGF-1 levels had an increased probability of surgical failure." (PMID 40590355, 2025). "In these types of tumors, the focus lies on the excessive secretion of growth hormone (GH) and Insulin-like growth factor 1 (IGF1), leading to acromegaly." (PMID 40362297, 2025). "Whereas the PASQ score focuses on symptoms and signs related to acromegaly, the ACRODAT® overall status emphasizes a combination of paraclinical (IGF1 levels, tumor size) and clinical factors (comorbidities, symptoms, and HRQoL)." (PMID 39959623, 2025). "To further explore the relationship between IGF1 normalization and HRQoL improvement, in this study, we assess in a real-world setting whether normalization of modestly elevated serum IGF1 would significantly impact clinical parameters and HRQoL in patients with acromegaly." (PMID 39959623, 2025). "In acromegaly patients, serum HbA1c, FBG, and IGF-1/x ULN were significantly higher (p = 0.01, p = 0.02, and p = 0.001, respectively)." (PMID 40186831, 2025). "The internationally accepted criterion for hormone remission in acromegaly includes a random GH < 1 ng/mL or GH nadir < 0.4 ng/mL after OGTT, with age‐ and sex‐adjusted normalization of IGF‐1." (PMID 40852938, 2025). "In the acromegaly treatment flowchart, PAS is recommended as a second- or third-line treatment in case of resistance to fg-SRLs, persistent GH or IGF-1 excess after surgery, or as a bridge treatment while awaiting the effects of radiotherapy." (PMID 39841390, 2025). "Biochemical tests, including serum insulin-like growth factor-1 (IGF-1) and nadir GH during oral glucose tolerant test (OGTT), are critical to diagnosing acromegaly." (PMID 39044175, 2024). "NF-κB is exaggerated in active acromegaly by the effect of IGF-1; thus, inhibition of IGF-1 by octreotide inhibits NF-κB expression with attenuation of systemic inflammation." (PMID 37584889, 2024). "It correlates with IGF-1 levels and the SAGIT acromegaly score and can be used to predict remission of the disease." (PMID 39202522, 2024). "Interactions between GH/IGF-1 and OPG/RANK-L system are complex and probably change in time, depending on how effectively the acromegaly is controlled and on other regulating mechanisms." (PMID 39741885, 2024). "Recently, a prospective study observed normalization of IGF-1 in 3 of 8 patients and reduction of IGF-1 in 2 of 8 patients in female patients with uncontrolled acromegaly." (PMID 39224564, 2024). "Pegvisomant is a growth hormone (GH) receptor antagonist that effectively lowers the insulin-like growth factor 1 (IGF-1) levels and improves symptom control in acromegaly." (PMID 38628593, 2024). "successfully distinguished individuals with abnormally high levels of insulin-like growth factor-1 (IGF-1) and accurately identified patients with acromegaly by using a machine learning model using microbiome composition." (PMID 38027221, 2023). "One study that investigated the interplay between IGF-1, abnormal growth hormone levels, altered mandibular growth and form, and OSA, reported that OSA was present across 83% of patients with acromegaly." (PMID 37241010, 2023). "Serum ANGPTL-8 levels, IGF-1, and GH were significantly lower in those with NAFLD in the acromegaly group." (PMID 37590020, 2023). "The results showed that serum phosphorus significantly correlated with IGF-1 and SAGIT scores for patients with active acromegaly." (PMID 38137499, 2023). "An excess incirculating GH and IGF-1, most commonly due to a pituitary adenoma and rarely dueto ectopic GH secretion or GHRH excess, leads to acromegaly." (PMID 39076279, 2023).
acromegaly (continued). "This study aims to assess the potential of the use of phosphorus and calcium as biomarkers in the clinical evaluation of patients with acromegaly and clarify their relationship with SAGIT and other common biomarkers (GH, IGF-1) in larger population sizes." (PMID 38137499, 2023). "Therefore, we assume that neuropathic pain and neuropathic-like pain symptoms in acromegaly are likely to be caused by acromegalic comorbidities (e.g. neuro-toxic metabolic dysregulation, or compression neuropathies), and not directly by GH and IGF-1 excess." (PMID 34687408, 2022). "Moreover, patients with acromegaly treated with either GH-receptor antagonists or somatostatin analogues represent a peculiar setting that need to be studied in depth to define safety and efficacy of both drug classes and their interaction with the GH/IGF-1 axis." (PMID 35265043, 2022). "As expected, IGF-1-ULN and GH were increased in patients with active acromegaly than those in remission (p<0.001 and p<0.001, respectively)." (PMID 35340319, 2022). "As expected, IGF-1-ULN and GH were increased in the group of patients with acromegaly (p<0.001 and p<0.001, respectively)." (PMID 35340319, 2022). "This study revealed that GH and IGF-1 levels, as well as concomitant hypogonadism, play an active role in the increase in calcium, ALP, and CTX levels in patients with acromegaly." (PMID 35340319, 2022). "Long-term treatment of acromegaly with OCT and lanreotide has been widely studied and showed normalization of GH and IGF-1 levels in about 20–70% and tumor shrinkage in 36–75% of patients." (PMID 34128215, 2022). "IGF-1 is also known to affect bone remodelling in periodontal tissue due to an increase in the levels of local BMP levels, as reported in patients with acromegaly." (PMID 35285598, 2022). "In our study, calcium, phosphorus, IGF-1-ULN, and GH levels were higher in patients with active acromegaly compared to those in controlled disease activity with medical or surgical treatment." (PMID 35340319, 2022). "While serum IGF-1 levels, basal GH values, and nadir GH after OGTT play a major role in the diagnosis, management, and treatment of patients with acromegaly, the limitations of these tests should be acknowledged for optimal use." (PMID 33803429, 2021). "It is known that the increased growth hormone (GH) and insulin-like growth factor-1 (IGF-1) have mitogenic and antiapoptotic properties in breast cells in acromegaly." (PMID 34530525, 2021). "Somatotroph PitNET are growth hormone (GH) hypersecreting, leading to overproduction of insulin-like growth factor 1 (IGF-1) and resulting in gigantism in children and acromegaly in adults." (PMID 34299200, 2021). "Acromegaly in CNC: In up to 75% of patients with CNC, the asymptomatic elevation of GH, IGF-1 and/or prolactin or abnormal response to the thyrotropin-releasing hormone is observed." (PMID 33805450, 2021). "Medical treatment of acromegaly with somatostatin analogs (LA-SMSA) and the GH receptor antagonist, pegvisomant (PEGV), has made it possible to achieve normal serum IGF1 concentrations in most patients with acromegaly." (PMID 33810319, 2021). "High insulin-like growth factor 1 (IGF-1) and unsuppressed growth hormone (GH) levels after glucose load confirm the diagnosis of acromegaly." (PMID 34081617, 2021). "This implies that GH/IGF-1, inflammation and CVD are closely, but complexly, intertwined in patients with acromegaly." (PMID 32458292, 2020). "Whereas the ex vivo dose-response curve following IGF-1 stimulation is linear, mononuclear cells obtained from patients with GHD and acromegaly both display a pro-inflammatory phenotype." (PMID 32458292, 2020). "Acromegaly patients managed on Somatostatin receptor ligands (SRLs), the most common first-line pharmacotherapy for acromegaly, may still experience acromegaly symptoms such as headache, sweating, fatigue, soft tissue swelling, and joint pain, even those with normal IGF-1." (PMID 32736547, 2020).
acromegaly (continued). "Negative correlations between serum asprosin levels and the course of acromegaly, IGF-1 SDS, GH-Nadir, and GH-AUC in acromegaly patients were also observed." (PMID 33414826, 2020). "Changes in the levels and burdens of GH and IGF-1 and body composition were linearly correlated with intraoperative NMB in acromegaly patients." (PMID 33414825, 2020). "This significant burden of disease and inadequate symptom control, particularly for individuals with IGF-1 < = 1 ULN, indicates an unmet need for patients with acromegaly." (PMID 32736547, 2020). "With a decreasing percentage of body fat and increasing GH, IGF-1, GH burden, and IGF-1 burden, the DNMBD and CNMBD both significantly decreased in a linear manner in acromegaly patients." (PMID 33414825, 2020). "In contrast, the indices of β-cell function were significantly lower in patients of acromegaly with hyperglycaemia, despite significantly higher GIP levels, with comparable IR indices and GH/IGF-1 levels." (PMID 30948746, 2019). "In our study, it was thought that IGF-1 and SBP levels were most closely related to CS in patients with acromegaly, and that this parameter should be closely monitored for the development of renal parenchymal disease due to CS relationship." (PMID 30653179, 2019). "Increased IGF-1 levels and increased SOS levels are closely related in patients with acromegaly, so that patients with higher IGF-1 levels need closer follow-up." (PMID 30653179, 2019). "Online Resource 4 contains an extensive checklist of the advised reporting of IGF-1, GH, OGTT and PK results in acromegaly studies." (PMID 29605877, 2018). "Our data have revealed that in the case of acromegaly, NDRG2 gene mRNA expression is significantly lower than in other diagnosis of PAs and PA that secretes hormones GH and IGF-1 hormones have low NDRG2 gene expression level as well." (PMID 28390436, 2017). "Studies on patients with acromegaly also demonstrated an enhancement in IGF-1 levels and the rate of multinodular goiter, suggesting a goitrogenic action of IGF-1." (PMID 29081797, 2017). "Additionally, we do not know whether these persistently elevated concentrations of IGF-1 increase the risk of comorbidities despite the absence of acromegaly, remembering that all of these patients had comorbidities." (PMID 28977166, 2017). "The current diagnosis of acromegaly is dependent upon both the oral glucose tolerance test (OGTT) and serum levels of insulin-like growth factor-1 (IGF-1)." (PMID 27517036, 2016). "The results showed that clinically significant tumor shrinkage (≥20 %) was achieved in 63 % of patients and there were early and sustained improvements in growth hormone (GH) and insulin-like growth factor-1 (IGF-1) levels, acromegaly symptoms, and HRQoL." (PMID 26603536, 2016). "Additionally, we do not know whether these persistently elevated concentrations of IGF-1 increase the risk of comorbidities despite the absence of acromegaly, remembering that all of these patients had a combination of two or more of these comorbidities." (PMID 27982199, 2016). "Low IGF-1 in the presence of clinical acromegaly could also represent a later stage of a disease process that was initially associated with elevated IGF-1, resulting in clinical features of acromegaly, but that has now “burnt out” (that is, burnt-out acromegaly)." (PMID 26514337, 2015). "We are unaware of the development of any antibody against GH or IGF-1, but several classes of compounds that inhibit the GH/IGF-1 axis have been approved for use in patients with acromegaly." (PMID 25902704, 2015). "Since, in parallel with people suffering from DM, endogenous insulin concentrations can be low in feline DM, a low IGF-1 reading could be obtained when sampling takes place prior to initiation of exogenous insulin treatment despite the presence of excess growth hormone due to acromegaly." (PMID 26023776, 2015).
acromegaly (continued). "In a large, randomized, 12-month, Phase III core study in medically naïve patients with acromegaly, pasireotide long-acting release (LAR) was significantly superior (P = 0.007) to octreotide LAR at providing GH <2.5 μg/L and normal IGF-1." (PMID 25103549, 2015). "Biochemical parameters, including growth hormone (GH) and insulin-like growth factor-1 (IGF-1) levels, established acromegaly; a head magnetic resonance imaging (MRI) scan revealed a small gadolinium-enhanced pituitary mass of 3 × 5 × 3mm." (PMID 24428849, 2014). "He underwent rigorous workup for CNC which revealed elevated insulin-like growth factor 1 (IGF-1) levels, and positive oral glucose tolerance test with pituitary microadenoma on MRI consistent with acromegaly." (PMID 24886234, 2014). "Moreover, IGF1 bioactivity was more strongly related to physical measures of QoL than total IGF1, suggesting that IGF1 bioactivity may better reflect physical limitations perceived in active acromegaly." (PMID 24692508, 2014). "Hormonal parameters showed IGF-1 to be 20.1 nmol/l (normal range: 14–40.5), serum GH during OGTT was: 0 min 2.7 mUI/l; 60 min 1.6 mUI/l; 120 min 1.4 mUI/l (criteria for acromegaly control: basal GH<1 ng/ml (3 mIU/l) and <0.4 ng/ml (1.2 mIU/l) during OGTT11)." (PMID 25210615, 2014). "Acromegaly is a rare but severe hormonal disorder resulting from aberrant GH (growth hormone) secretion and consequent increase of IGF-I (insulin-like growth factor 1), most commonly produced by pituitary adenomas." (PMID 23593161, 2013). "These uncertainties render the role of IGF-1 or the GH nadir during OGTT as the sole parameter for the estimation of prognosis (recurrence, morbidity, and mortality) of acromegaly problematic." (PMID 22550484, 2012). "As IGF-1 has a long half-life of 18 to 20 hours, IGF-1 level is recommended as the best initial screening test for all patients suspected of having acromegaly." (PMID 23209463, 2012). "Hepatic malignancy can rarely produce IGF-1 or cortisol-like substances, leading to acromegaly-like features and hypercortisolism independent of pituitary GH or ACTH secretion." (PMID 41497147, 2026). "In conclusion, the rate of colon polyps was higher in patients with acromegaly, regardless of age, gender, presence of DM, adenoma size, or IGF-1 and GH levels in the present cohort." (PMID 40167828, 2025). "Additionally, comorbidities related to long-standing exposure to increased growth hormone (GH) and IGF-1 levels, including hypertension (HTN) and abnormal glucose control, are prevalent in acromegaly." (PMID 40385738, 2025). "Patients also had markedly elevated hormone levels (median fasting GH 10.9 μg/L; mean IGF-1 923 ± 385 μg/L in those without cancer), reflecting the biochemical severity of acromegaly." (PMID 41293738, 2025). "The precise role of IGF-1 in the pathophysiology of LVM in acromegaly is still not fully understood." (PMID 40429391, 2025). "In addition to normalizing IGF1 levels, PEGV has been demonstrated to have a positive impact on patients’ HRQoL, symptoms and signs of acromegaly and comorbidities (especially dysglycemia)." (PMID 39959623, 2025). "This aligns with studies in treated acromegaly patients, where GH and IGF-1 were also not major determinants of residual cardiometabolic risk." (PMID 41307388, 2025). "The key finding of our study is that changes in lean mass, which are directly influenced by GH/IGF-1 overproduction, could play an important role in the pathogenesis of LVH and in the enlargement of LA in acromegaly." (PMID 40429391, 2025). "Postoperatively, GH and IGF-1 levels decreased but did not normalize completely, and he continued to show clinical features consistent with acromegaly." (PMID 41479497, 2025).
acromegaly (continued). "In this phase 3 trial that included patients who had been receiving stable SoC treatment and had biochemically controlled acromegaly at screening, those who received CAM2029 demonstrated significantly greater biochemical disease control, measured as IGF-1 and GH over 24 weeks, compared to placebo." (PMID 39378125, 2025). "Growth hormone (GH) and IGF-1 levels at diagnosis in acromegaly patients with and without any type of cancer across published studies." (PMID 41293738, 2025). "Laboratory tests showed elevated serum GH (32.6 ng/mL) and IGF-1 (473 ng/mL) levels, as well as a lack of GH suppression after glucose administration, confirming the diagnosis of acromegaly." (PMID 41458762, 2025). "did not observe an association between IGF-1 levels and RANK-L/OPG ratio in patients with acromegaly." (PMID 39741885, 2024). "Nomoto reported a woman with acromegaly combined with autonomously functioning thyroid nodules with typical physical features of acromegaly and hyperthyroidism with TSH suppression, who returned to normal IGF-1 levels and thyroid function after treatment with octreotide." (PMID 38349236, 2024). "involving 36 acromegaly patients and 24 control subjects, which investigated the relationship between acromegaly and structural lung abnormalities, there was no statistical difference between serum IGF-1 level in patients with or without bronchiectasis." (PMID 39220366, 2024). "IGF-1 increased in the whole cohort, but remaining within normal range, except two patients, in whom acromegaly was ruled out with oral glucose tolerance test." (PMID 38902646, 2024). "Of particular interest is the frequency of GH-Par that emerges from this study in the non-acro↑IGF−1 group, which includes subjects with high IGF-1 levels and without acromegaly (excluded with the most sensitive threshold of GHnadir < 0.4 μg/L after OGTT)." (PMID 37344722, 2024). "Secondly, we intended to determine the prevalence of GH-Par in a series of subjects without acromegaly but with elevated IGF-1 levels." (PMID 37344722, 2024). "While a systematic evaluation of IGF-1 is not recommended during DA treatment unless symptoms or signs suggestive for incipient acromegaly develop." (PMID 38902646, 2024). "After multiple confirmations of isolated IGF1 levels above the upper normal limit (mean IGF1 SDS + 3.65), with a mean follow-up of 81 months from surgery, these patients started medical therapy for acromegaly." (PMID 38502285, 2024). "The diagnosis and recurrence of acromegaly were defined by both elevated IGF-1 levels and a lack of GH suppression based on appropriate criteria for the assay used at the time of diagnosis." (PMID 38502285, 2024). "Most studies conducted on groups of patients with acromegaly have not confirmed a direct influence of the GH/IGF-1 axis on sclerostin concentration, however, both positive and negative relationships have been observed." (PMID 39741885, 2024). "Clinically silent cases with elevated GH and IGF-1 were occasionally reported, but no reports of cases with acromegaly-related symptoms and normal hormone levels have been published to our knowledge." (PMID 39044175, 2024). "In addition, in the controlled acromegaly group, a positive correlation between Ff genotypes and IGF-1, as well as with IGF-1 according to the upper limit of normal, is revealed." (PMID 37446150, 2023). "An elevated IGF-1 level is diagnostic of GH excess, while a normal IGF-1 level effectively rules out the possibility of acromegaly." (PMID 37755395, 2023). "GH/IGF-1 overproduction in acromegaly leads to increased bone turnover with negative calcium balance." (PMID 37670889, 2023). "We found that GH and IGF-1 levels were lower in those with NAFLD than those without NAFLD in the patients with acromegaly." (PMID 37590020, 2023). "Screening for acromegaly is relatively simple and done with measurement of a random, non-fasting IGF-1 level that can be drawn at any time during the menstrual cycle." (PMID 36721176, 2023).